NPIPB6 (nuclear pore complex interacting protein family member B6)
Synonyms: NPIPB
Tractability: No criterion of Open Targets' tractability assessment is met for any kind of drug.
Gene: Protein-coding gene on chromosome 16 (28,342,517 to 28,363,508, reverse strand). Ensembl gene ENSG00000198156.
Subcellular location (Human Protein Atlas): Nucleoplasm
Genetic constraint (gnomAD): Loss-of-function variants: 2 observed, 8.48 expected, observed/expected ratio (o/e) 0.24, 90% interval 0.095 to 0.74. That is too few expected variants to judge how well the gene tolerates losing a copy. Missense variants: 93 observed, 147.88 expected, observed/expected ratio (o/e) 0.63, 90% interval 0.53 to 0.75. Synonymous variants: 34 observed, 49.22 expected, observed/expected ratio (o/e) 0.69, 90% interval 0.52 to 0.92.
Homologues: Paralogues in human: NPIPB9 (96% identical), NPIPB8 (96% identical), NPIPB15 (89% identical), NPIPB7 (88% identical), NPIPB13 (75% identical), NPIPB5 (75% identical), NPIPB11 (75% identical), NPIPB12 (75% identical), NPIPB4 (75% identical), NPIPB2 (64% identical), NPIPA3 (58% identical), NPIPA2 (57% identical), and 7 more.
Diseases named in the same sentence as NPIPB6 in open-access papers:
NPIPB6 is named in the same sentence as 2 diseases in open-access papers, as found by Europe PMC text mining. Sharing a sentence is not in itself a finding about the gene and the disease. The quoted sentences say what the papers report.
cancer (1 paper, 2021). A tumor composed of atypical neoplastic, often pleomorphic cells that invade other tissues. "MAMDC2 is a known tumor suppressor involved in glycosaminoglycan binding, whereas NPIPB6 has not previously been associated with cancers to the best of our knowledge." (PMID 34149812, 2021).
NPIPB6 also shares sentences with these, for which no sentence is quoted: tumor (1 paper).